DKK4 (dickkopf Wnt signaling pathway inhibitor 4)
Diseases named in the same sentence as DKK4 in open-access papers (continued):
Sharing a sentence is not in itself a finding about the gene and the disease.
schizophrenia (3 papers, 2008 to 2021). A major psychotic disorder characterized by abnormalities in the perception or expression of reality. "They reported that DKK4 was associated with schizophrenia with an odds ratio of 3.9 ( p.01, CI 1.3‐11.1 )." (PMID 33586359, 2021). "An association study of 28 Wnt signalling genes found the polymorphic variation rs2073665 in the Dkk4 gene (DKK4) to be associated with schizophrenia." (PMID 24403877, 2013). "Recently, the gene encoding DKK4, a component of the GSK-3/Wnt signaling cascade, was shown to be associated with schizophrenia." (PMID 18702828, 2008). "Interestingly, the DKK4 SNP, rs2073665 was found to be significantly associated with brain volume under both additive and dominant genetic models in 961 healthy Chinese individuals, thus strengthening the evidence for a neurodevelopmental hypothesis of schizophrenia." (PMID 24403877, 2013).
colorectal tumors (2 papers, 2013 to 2021). "DKK4 level was positively correlated with fibroblast growth factor‐20 and the accumulation degree of nuclear β‐catenin in colorectal tumours." (PMID 33586359, 2021). "DKK4 was confirmed to be upregulated in colorectal tumours and was shown increasing cell migration and invasion." (PMID 33586359, 2021). "Interestingly, our group also observed a significant inverse correlation between VDR and DKK-4 RNA levels in human colorectal tumors, suggesting that the regulation of DKK-4 observed in cell lines also occurs in patients." (PMID 24202444, 2013).
endometrial carcinoma (2 papers, 2012 to 2021). A malignant tumor arising from the epithelium that lines the cavity of the uterine body. "Similar to the other Dickkopf proteins, DKK4 controls the WNT signaling pathway; its differing expression and role in tumor genesis and tumor progression have already been described in multiple tumors, including endometrial carcinoma." (PMID 34503158, 2021). "Interestingly, upon reviewing gene expression profiles obtained from progressive and non-progressive endometrial cancer, a number of inhibitors of Wnt/β-catenin signaling were indeed found to be down-regulated in progressive disease (DKK1, DKK4 and WIF1)." (PMID 22295114, 2012).
gastrointestinal stromal tumor (2 papers, 2022 to 2024). "Aberrant accumulation of DKK4 promotes tumour progression via forming the immune suppressive microenvironment in gastrointestinal stromal tumour." (PMID 38519641, 2024). "DKK4 expression was closely correlated with poor prognosis of gastrointestinal stromal tumors." (PMID 36181792, 2022).
lymph node metastasis (2 papers, 2017 to 2023). "This association ((DKK4 level (HR = 2.18, 95% CI = 1.37–3.46, P = 0.001) and FIGO stage (HR = 2.21, 95% CI = 1.41–3.46, P = 0.001)) was also significant in the multivariate Cox model adjusted for age, cell differentiation, and lymph node metastasis." (PMID 28666421, 2017). "LARS and DKK4 expressions were not related to gender, age at surgery, histologic grade, size, tumor location, tumor invasion, or metastasis, but LARS expression was significantly correlated with TNM stage, N stage, and lymph node metastasis." (PMID 37096225, 2023).
medulloblastoma (2 papers, 2014 to 2025). A malignant, invasive embryonal neoplasm arising from the cerebellum. "In accord with previous reports, we identified distinct groups of co-expressed genes that were highly enriched for WNT signalling in WNT medulloblastoma, (including DKK1, DKK2, DKK4, WIF1, LEF1 and WNT16)." (PMID 25412507, 2014).
prostate carcinoma (2 papers, 2020 to 2022). A carcinoma that arises from epithelial cells of the prostate gland. "DKK4 gene amplification occurs in as many as 6% of metastatic prostate cancers, while homozygous deletion has also been observed in both primary (4–5.5%) and metastatic cases (1.6–3.6%)." (PMID 35204808, 2022). "DKK4 appears to play a similar role to DKK1 to antagonize the Wnt/β-catenin pathway, and relative to all other DKK family members, genetic variants in DKK4 are more common in prostate cancer." (PMID 35204808, 2022).
benign ovarian tumor (1 paper, 2017). "We found that the relative fold of DKK4 mRNA was significantly increased in EOC tissues (3.63 ± 2.84) than that in benign ovarian tumor tissues (1.66 ± 1.36) (p = 0.001)." (PMID 28666421, 2017). "The relative level of DKK4 protein was significantly upregulated in EOC tissues (0.86 ± 0.01) than that in benign ovarian tumor tissues (0.37 ± 0.03) (p < 0.0001)." (PMID 28666421, 2017). "We compared the expression of DKK4 mRNA and protein in human EOC tissues and benign ovarian tumor tissues by qRT-PCR and western bolt." (PMID 28666421, 2017). "The expressions of DKK4 mRNA and protein were elevated in EOC tissues as compared with those in benign ovarian tumors (p = 0.001 and <0.0001 respectively)." (PMID 28666421, 2017). "QRT-PCR and western blot analysis were used to examine the levels of DKK4 mRNA and protein in 33 EOC tissues and 33 benign ovarian tumors." (PMID 28666421, 2017).
brain tumor (1 paper, 2023). "To compare the data quality of RRST and standard Visium datasets obtained from the pediatric brain tumor samples, we examined the expression of WNT-signaling genes, including AXIN2, DKK4, LEF1 and CTNNB1 and two known targets of the WNT pathway SP5, GAD122,23." (PMID 36720873, 2023).
cataract (1 paper, 2010). Partial or complete opacity of the crystalline lens of one or both eyes that decreases visual acuity and eventually results in blindness. "However, like Ta mice, the transgenic mice lacked meibomian glands associated with their eyelids and developed visible cataracts at around 6 months of age, suggesting that meibomian gland development is Dkk4-responsive." (PMID 20386733, 2010).
colon adenocarcinoma (1 paper, 2024). "Indeed, 1597 was derived from the samples of colon adenocarcinoma with lower DKK4 expression." (PMID 38519641, 2024).
dementia (1 paper, 2025). Loss of intellectual abilities interfering with an individual's social and occupational functions. "Moreover, MMP12 and DKK4, the most critical proteins in the other two clusters, have been confirmed as plasma biomarkers significantly associated with dementia in various studies." (PMID 40748327, 2025).
Hyperglycemia (1 paper, 2016). An increased concentration of glucose in the blood. "Hyperglycemia diminishes DKK4 protein which causes activation of canonical Wnt signaling pathway through Wnt3a ligand mediated enhanced translocation of β–catenin into nucleus, thereby promoting proliferation of HCC cells." (PMID 27272409, 2016).
lentivirus infection (1 paper, 2022). Virus diseases caused by the Lentivirus genus. "To further explore the roles of DKK4 in CRC, we established gain-of-function models of DKK4 in Caco-2 and HCT8 cells through lentivirus infection and established loss-of-function models of DKK4 in SW480 and HCT116 cells using a lentiviral vector carrying shRNA." (PMID 36181792, 2022).
melanoma (1 paper, 2014). A malignant, usually aggressive tumor composed of atypical, neoplastic melanocytes. "DKK1 and DKK2 were undetectable in B16F10 melanoma cells, whereas DKK3 and DKK4 were expressed." (PMID 24091497, 2014).
osteoporosis (1 paper, 2021). A condition of reduced bone mass, with decreased cortical thickness and a decrease in the number and size of the trabeculae of cancellous bone (but normal chemical composition), resulting in increased fracture incidence. "Bioinformatics analysis showed that DKK4 is the target gene of H19, and through the Wnt/β-catenin pathway to mediate the biological effects of H19 in disused osteoporosis." (PMID 34583640, 2021).
ovarian tumors (1 paper, 2024). "When BRCA2mt ovarian tumors were compared with BRCA1mt tumors, eight genes (NOTUM, SFRP5, RNF43, ZNRF3, DKK1, DKK4, NKD1, and AXIN2) that negatively regulate Wnt signaling were upregulated in BRCA2mt tumors." (PMID 39028933, 2024).
rectal adenocarcinoma (1 paper, 2024). "The two tissue samples of rectal adenocarcinoma carried almost equal DKK4 protein levels." (PMID 38519641, 2024).
thymoma (1 paper, 2022). A neoplasm arising from the epithelial cells of the thymus. "SFRP2 and SFRP5 expression levels were increased in B2 thymomas, while AB thymomas showed increased DKK1 and DKK4 expression compared to other TETs and NTs." (PMID 35965500, 2022).
tumor (25 papers, 2009 to 2025). "In this study, we discovered that tumor‐derived DKK4 is correlated with high‐risk stratification and poor prognosis of GIST patients." (PMID 31353847, 2019). "Given that DKK4 is overexpressed in high‐risk GISTs and responsible for patients’ poor prognosis, we demonstrate that it potentiates to be an excellent tumor marker for predicting individual's survival and monitoring recurrence." (PMID 31353847, 2019). "This pathway constituted 19 upregulated and 15 downregulated genes, amongst which were DKK1 and DKK4, which were the two most upregulated genes in the G3 tumor." (PMID 39245631, 2025). "The results confirm that the transformation of fibroblasts by DKK4 at primary tumour sites restricts tumour growth and enhances the metastasis of CRCs." (PMID 38519641, 2024). "Taken together, it is very useful to analyze the expression of LARS and DKK4 simultaneously when examining tumor sections at the diagnosis of CRC to predict the recurrence and OS of CRC patients." (PMID 37096225, 2023). "DKK4 expression and tumor invasion were independent prognostic factors for DFS (HR = 2.01, 95% CI: 1.20–3.37, p = 0.008; HR = 3.02, 95% CI: 1.22–7.46, p = 0.017, respectively)." (PMID 37096225, 2023). "In hepatocellular carcinoma, DKK4 expression is reduced, and its induction suppresses tumor progression and proliferation." (PMID 36181792, 2022). "Overall, our studies demonstrated that DKK4 inhibits tumor metastasis in CRC and uncovered a novel regulatory mechanism through the Wnt3a/DKK4/AKT/s552 β-catenin negative feedback loop in CRC." (PMID 36181792, 2022). "Since Wnt3a is an abundant growth factor in the CRC tumor microenvironment that is conducive to metastasis, this finding provides a rationale for why DKK4 is upregulated in tumors but plays a suppressive role." (PMID 36181792, 2022). "To investigate the underlying mechanism by which DKK4 inhibits tumor metastasis in CRC, we performed RNA-seq to identify potential DKK4-regulated molecules." (PMID 36181792, 2022). "In summary, we found for the first time that DKK4 is upregulated in CRC but plays a suppressive role in tumor metastasis." (PMID 36181792, 2022). "Like the other three family members, the role of DKK-4 has been described as both a tumor suppressor and oncogene in various cancers." (PMID 34451907, 2021). "DKK4 is not only involved in tumour growth, invasion, migration and chemotherapy resistance, but also in osteoblastogenesis and secondary hair or meibomian gland formation." (PMID 33586359, 2021). "The effect of DKK4 and TRα1 on tumor growth and metastasis of J7 in animal models was observed without treating T3." (PMID 32528965, 2020). "In contrast of DKK2 gene, there was significant correlation between DKK4 promoter methylation and tumor grade (P=0.03)." (PMID 33346226, 2020). "In the other hand, defining the exact role of Wnt pathway as proliferative or antiproliferative signaling modules can clarify the possible character of DKK2 and DKK4 genes as weather they are tumor suppressor genes or oncogenes in pathogenesis of OSCC." (PMID 33346226, 2020). "Consistent with findings elicited from tumor tissue, the inspiring results made it clear that DKK4 was a proper tumor biomarker for auxiliary diagnosis and recurrence monitor with individual peripheral blood samples." (PMID 31353847, 2019). "We found that DKK4 was specifically located around tumor cells region, indicating that it belongs to tumor‐derived secretory protein." (PMID 31353847, 2019). "Subsequently, proved by the co‐culture apoptosis assay of tumor cells and CD8+ T cells, deregulation of DKK4 had a distinct impact on tumor cells’ biological behavior with stromal immune cells existing." (PMID 31353847, 2019). "Consistently, these data illustrated that tumor cells‐derived DKK4 decreased the infiltrating of cytotoxic immune cells to avoid antitumor immune response, which universally happened in humans." (PMID 31353847, 2019).
tumor (continued). "Our study supports that DKK4 is not only a good candidate for tumor marker, but also a potential therapeutic target to improve the effects of combined therapy." (PMID 31353847, 2019). "We found that serum DKK4 concentration was decreased to a large extent with the tumor excised from body." (PMID 31353847, 2019). "Complementary to the loss-of-function experiments, SHP, DKK4, or CADM4 overexpression significantly reduced tumor formation in immunocompromised mice." (PMID 28273073, 2017). "In sum, we have shown that DKK4 was over-expressed, predicated poor prognosis and promoted tumor invasion through acitvating JNK in EOC carcinogenensis." (PMID 28666421, 2017). "Only DKK4 exhibited similarly high methylation levels in both tumour and normal specimens, while DACT1 was always essentially unmethylated." (PMID 22672427, 2012). "The results showed that the numbers and volumes of tumour masses in the lungs were dramatically higher in the mice injected with cancer cells (1597, 3117 and 3431) with control shRNA than in the mice injected with cells with reduced DKK4 expression." (PMID 38519641, 2024). "Interestingly, tumor invasion and DKK4 low expression were independent poor prognostic factors of DFS in CRC patients." (PMID 37096225, 2023). "We examined the effects of DKK4 on cell proliferation and metastasis by cell counting kit-8 assays, transwell assays, and subcutaneous and metastatic mouse tumor models, and we discovered that DKK4 silencing promoted the metastasis of CRC cells both in vitro and in vivo." (PMID 36181792, 2022). "Besides the studies that identify its possible role as a tumor suppressor or oncogene, DKK-4 expression has been strongly related to cancer cell migration." (PMID 34451907, 2021). "Strikingly, they found that ligand-dependent tumours tend to silence genes encoding Wnt antagonists, such as AXIN2, NKD1, APCDD1, NOTUM, and DKK4, whereas ligand-independent tumours effectively bypass Wnt-pathway negative feedback loops without the need for such selective pressure." (PMID 33673710, 2021). "The results showed that SRC‐2 activation of DKK4 could inhibit the occurrence of tumours in vivo and in vitro." (PMID 33586359, 2021). "DKK4 proteins can inhibit the activity of Wnt/β‐catenin signalling pathway, and the deregulation of this feedback in some tumours might promote tumour development." (PMID 33586359, 2021). "The tumor growth and metastatic index were repressed by overexpression of DKK4 and TRα1." (PMID 32528965, 2020). "Significant correlation was found between DKK4 promoter methylation and tumor grade." (PMID 33346226, 2020). "Hypomethylation of DKK2 and DKK4 genes in higher grades of OSCC samples may indicate the pivotal role of their expression in tumor cells invasion and progression through modulation of Wnt signaling pathway." (PMID 33346226, 2020). "In addition, we present a new mechanism for tumor cells to evade immunological elimination, via secreting DKK4 to inactivate immune response." (PMID 31353847, 2019). "Based on these analyses, we designed a chemotaxis assay of PBMCs, which demonstrated that tumor cells‐derived DKK4 could inhibit migration of cytotoxic immune cells." (PMID 31353847, 2019). "All these clinical data supposed that DKK4 served as a promoting tumor factor in GIST." (PMID 31353847, 2019). "Thus, multiple SRC-2 target genes, including SHP, CADM4, and DKK4, exhibit tumor suppressor activity in human HCC cells." (PMID 28273073, 2017). "However, DKK4 was later found that upregulated in human cancer, promoted tumor cell invasion and angiogenesis." (PMID 28666421, 2017). "Since DKK4 affects cell migration, the level of DKK4 expression may serve as a metastatic switch critical for tumor metastasis." (PMID 27806330, 2016). "This is in agreement with the recent reports on the relationship between DKK4 and tumor metastasis." (PMID 27806330, 2016). "Moreover, DKK4 overexpression partially rescued tumour proliferative and anti‐apoptotic effects." (PMID 37070251, 2023).
tumor (continued). "In addition, tumor‐derived DKK4 could decrease immune cells infiltration and activation in the tumor microenvironment, which decreased the antitumor effects in return." (PMID 31353847, 2019). "However, DKK4 remains weak understanding of its major function in GIST tumor progression." (PMID 31353847, 2019). "DKK4 firstly, could act as a tumor suppressor by inhibiting the Wnt pathway." (PMID 28666421, 2017). "DKK3 and DKK4 could be referred as the putative tumor suppressors." (PMID 27457487, 2016). "In both comparisons, the most pronounced genes in WNT signaling‐related pathways are DKK4 and DKK1, as in both comparisons, these two genes were highly upregulated in G3 tumor." (PMID 39245631, 2025). "We tested TNM stage, tumor invasion, N stage, LN metastasis, metastasis, and the combination of LARS and DKK4 expressions in the Cox proportional hazard model." (PMID 37096225, 2023). "We also found that tumor invasion and LARS high/DKK4 low expression were independent poor prognostic factors of DFS." (PMID 37096225, 2023). "For DFS in CRC patients, tumor invasion and LARS high/DKK4 low expression were independent poor prognostic factors (HR = 3.14, 95% CI: 1.27–7.76, p = 0.013; HR = 3.04, 95% CI: 1.52–6.09, p = 0.002, respectively)." (PMID 37096225, 2023). "Analysis of leading-edge genes within the NR signature identified five consensus differentially expressed NRs in the two discovery cohorts, all expressed at a significantly higher level in LI versus LD tumours—AXIN2, NKD1, APCDD1, NOTUM and DKK4." (PMID 31563876, 2020). "It was surprising that knockdown of DKK4 had little effect on biological behavior of GIST cell line, which reminded us of the possibility that DKK4 promoted tumor progress by contacting with stromal cells." (PMID 31353847, 2019). "Downregulation of DKK4 expression showed no impact on the luminescence intensity, growth rate, or tumor weight between the two groups." (PMID 36181792, 2022). "Hypomethylation of DKK2 and DKK4 genes in higher grades of OSCC tissue samples may indicating their overexpression and thereby tumor progression through suppressing Wnt pathway." (PMID 33346226, 2020). "This indicated that tumor cells‐derived DKK4 directly inhibited CD8+ T cells migrating, and this effect could be eliminated by DKK4 knockdown." (PMID 31353847, 2019). "Indeed, enforced expression of SHP, CADM4, DKK4, and THSRP in combination significantly reduced proliferation and tumor burden." (PMID 28273073, 2017). "In contrast, overexpression of either DKK4 or THRSP alone significantly impacted rates of cell proliferation but not tumor burden." (PMID 28273073, 2017). "However, a closer look at the respective genes reveals that many of them (SFRP5, WISP3, DKK4, FRZB and JUP) are antagonists of the 'WNT-beta catenin' pathway, thus exerting a tumor suppressor role in normal conditions." (PMID 19327144, 2009). "However, DKK4 expression, tumor invasion, and TNM stage were not independent prognostic factors for OS (p = 0.081, p = 0.063, and p = 0.697, respectively)." (PMID 37096225, 2023). "Overexpression of DKK4 slightly abolished the malignancy of GIST‐430 cells, which is supposed to be that, redundant DKK4 in vitro could only target the tumor cells to inhibit their Wnt signaling, without an integrated coping mechanism for DKK4 accumulation and other TME stromal cells existing." (PMID 31353847, 2019). "However, it is important to note that DKK4 mRNA and protein levels did not correlate in the SRC-2 gain-of-function and loss of function studies, and that overexpression of DKK4 alone was insufficient to rescue the tumor burden of SRC-2 knockdown in HepG2 cells." (PMID 28273073, 2017).